UQCC6 (ubiquinol-cytochrome c reductase complex assembly factor 6)
Description:
Required for the assembly and stability of the mitochondrial ubiquinol-cytochrome c reductase complex (complex III (CIII) or cytochrome b-c1 complex), a multisubunit transmembrane complex that is part of the mitochondrial electron transport chain (ETC) which drives oxidative phosphorylation. Mediates early complex III biogenesis (By similarity). Participates in regulating the levels of electron transport chain proteins, and therefore energy supply, in response to changes in energy demand (By similarity). Also required for cytochrome c oxidase complex (complex IV) assembly.
Synonyms: BR; BRAWNIN; C12orf73; FLJ13975; DKFZp547P055
Tractability: Antibody: UniProt predicts a signal peptide or a membrane-spanning region; the Human Protein Atlas places it where antibodies can reach. PROTAC: ubiquitination databases record sites on it.
Gene: Protein-coding gene on chromosome 12 (103,940,763 to 103,965,722, reverse strand). Ensembl gene ENSG00000204954.
Subcellular location: Mitochondrion inner membrane
Subcellular location (Human Protein Atlas): Centrosome; Mitochondria; Plasma membrane
Pathways (Reactome):
Metabolism: Complex III assembly
Gene Ontology:
Molecular function: protein binding
Biological process: mitochondrial respiratory chain complex III assembly; mitochondrial respiratory chain complex IV assembly
Cellular component: mitochondrial inner membrane; mitochondrion
Genetic constraint (gnomAD): Loss-of-function variants: 1 observed, 1.14 expected, observed/expected ratio (o/e) 0.88, 90% interval 0.25 to 1.88. That is too few expected variants to judge how well the gene tolerates losing a copy. Missense variants: 55 observed, 40.51 expected, observed/expected ratio (o/e) 1.36, 90% interval 1.09 to 1.7. Synonymous variants: 12 observed, 14.65 expected, observed/expected ratio (o/e) 0.82, 90% interval 0.52 to 1.33.
Homologues: Orthologues: chimpanzee UQCC6 (100% identical), macaque UQCC6 (93% identical), rabbit UQCC6 (86% identical), guinea pig UQCC6 (83% identical), dog UQCC6 (82% identical), mouse Uqcc6 (77% identical), pig UQCC6 (76% identical), rat Uqcc6 (73% identical), zebrafish uqcc6 (65% identical), tropical clawed frog uqcc6 (61% identical).
Diseases named in the same sentence as UQCC6 in open-access papers:
UQCC6 is named in the same sentence as 5 diseases in open-access papers, as found by Europe PMC text mining. Sharing a sentence is not in itself a finding about the gene and the disease.
UQCC6 shares sentences with these, for which no sentence is quoted: autism spectrum disorder (1 paper); breast carcinoma (1); neurodevelopmental disorder (1); neuromuscular disease (1); Vertigo (1).